AR (androgen receptor)
Diseases named in the same sentence as AR in open-access papers (continued):
Sharing a sentence is not in itself a finding about the gene and the disease.
prostate carcinoma (continued). "The effects of AR and AR-V7 on prostate cancer cell viability and migration are mediated by their impact on gene expression." (PMID 38410785, 2024). "Given that nuclear AR protein drives transcriptional activity that is important for prostate cancer proliferation and survival, we assessed nuclear AR expression." (PMID 38566104, 2024). "While previous research has concentrated on AR in prostate cancer, the common pathway between bone metastasis and prostate cancer remains largely unexplored." (PMID 39705435, 2024). "The prostate cancer pathway was chosen to model the AR signaling cascade, containing many of its component genes, such as AR, CREBBP, and PTEN." (PMID 38542265, 2024). "SCD has been shown to promote proliferation and disease progression in prostate cancer by affecting cellular signaling cascades and modulating androgen receptor transactivation." (PMID 39335669, 2024). "Further research is needed to fully elucidate the role of AR in prostate cancer and its interactions with other signaling pathways." (PMID 39600743, 2024). "Together, these data indicate that CDK2 inhibition represents a novel therapeutic approach to treat prostate cancers progressing on AR signaling inhibition and exhibiting phenotypic plasticity that includes increased expression and function of MYBL2." (PMID 39113611, 2024). "GR has been implicated as a clinically relevant AR substitute in advanced prostate cancer, recapitulating AR signalling." (PMID 39088439, 2024). "The potential of various biomarkers such as gene fusions (TMPRSS2-ERG), noncoding RNAs (SNHG12), proteins (PSA, PSMA, AR), and circulating tumor cells (CTCs) in the diagnosis, prognosis, and targeted therapies of prostate cancer is emphasized." (PMID 40353136, 2024). "While the oncogenic role of GR in enzalutamide-treated AR-positive prostate cancer is well-established, its role in AR-negative subtypes has remained elusive." (PMID 39027480, 2024). "The AR signaling axis plays a key role in the progression of prostate cancer, including in the lethal chemotherapy‐resistant form of CRPC that arises from ADT failure." (PMID 38958553, 2024). "mRNA PCA3 plays an essential role in prostate cancer cell survival by modulating androgen receptor signaling." (PMID 38254807, 2024). "The most extensively studied function of GR in prostate cancer is its ability to bypass androgen blockade in AR-positive prostate cancer." (PMID 39027480, 2024). "Next, we utilized a VCaP castration-resistant prostate cancer model (VCaP-CRPC) for further assessment of CBPD-409 anti-tumor efficacy alone or in combination with the AR antagonist enzalutamide." (PMID 38586029, 2024). "Other CD44 isoforms, such as CD44v9 in prostate cancer cells, stabilize the androgen receptor (AR) through MET signaling." (PMID 39769452, 2024). "A-485 was reported as a potent, selective and drug-like catalytic inhibitor of CBP/p300 that competes with acetyl coenzyme A. A-485 selectively inhibits the proliferation of hematological malignancies and AR+ prostate cancer." (PMID 39407454, 2024). "This is particularly relevant in prostate cancer treatments, where dysfunctional mitochondria can affect the stability and activity of the AR." (PMID 39296545, 2024). "The androgen receptor (AR) is a ligand-induced transcription factor that is predominantly expressed in primary prostate cancer and metastatic tumors." (PMID 39567496, 2024). "Crosstalk between these pathways and AR signaling can enhance the growth and survival of prostate cancer cells." (PMID 39184676, 2024). "Pharmacologic inhibition of PDE4D also suppresses prostate cancer growth by blocking sonic hedgehog, androgen receptor and MAPK pathways, and reverse tamoxifen resistance in estrogen receptor-positive breast cancer." (PMID 38233872, 2024). "The first VHL-based PROTAC, targeting the androgen receptor (AR) in prostate cancer, was developed in 2012, while the first CRBN-based PROTAC, targeting BRD4, followed in 2015." (PMID 39649701, 2024).
prostate carcinoma (continued). "Prostate adenocarcinomas are predominantly driven by aberrant AR signaling, with the majority of primary prostate cancer tumors being AR-positive and androgen dependent." (PMID 39027480, 2024). "Examples of this include targeting the AR pathway in prostate cancer and the PAX3-FOXO1 fusion pathway in rhabdomyosarcoma through inhibition of the BAF complex." (PMID 39536500, 2024). "In the context of the AR/ER crosstalk, several studies have focused on the role of ENZ, an AR inhibitor (commonly used for prostate cancer) in BC models." (PMID 39650747, 2024). "These compounds were evaluated for antiproliferative activity in both androgen receptor (AR)-positive and AR-null prostate cancer cell models using WST-1 cell proliferation assay." (PMID 39770110, 2024). "The authors further reported that combined treatment with MLN4924 and an AR antagonist significantly suppressed prostate cancer cell growth." (PMID 39623094, 2024). "In a large panel comprising 131 human-derived normal and cancer cell lines, CBPD-409 shows preferential cytotoxicity in AR-driven prostate cancer versus normal prostate and other cancer models." (PMID 38586029, 2024). "The process of prostate cancer cell proliferation, differentiation, and metastasis is aided by androgen-mediated transcription of AR target genes." (PMID 39114070, 2024). "Androgen receptor (AR) plays a central role in prostate cancer (PCa) development, and androgen deprivation therapy (ADT) to reduce levels of circulating androgens (testosterone and dihydrotestosterone, DHT) is the standard treatment for metastatic PCa." (PMID 38182874, 2024). "Our simulations revealed prolonged AR inhibition causes significant dysregulation of TGF-β, IDH1, and cell cycle pathways specifically in AA prostate cancer." (PMID 38566104, 2024). "Given these properties, ARD-1676 is viewed as an exceptionally promising candidate for the development of treatments for AR-positive human prostate cancer." (PMID 38675453, 2024). "The Notch pathway can also be activated to inhibit achaete‐scute family basic helix‐loop‐helix (BHLH) transcription factor 1 (ASCL1) expression for treating androgen receptor‐active prostate cancer (ARPC) and neuroendocrine prostate cancer (NEPC)." (PMID 39485722, 2024). "NSD2 expression is abnormally gained in prostate cancer cells and its functional inhibition impairs AR trans-activation potential through partial off-loading from over 40,000 genomic sites, which is greater than 65% of the AR tumor cistrome." (PMID 38464251, 2024). "For prostate cancer treatment, AR-targeted inhibitors, such as enzalutamide and bicalutamide, have been developed." (PMID 39547513, 2024). "Both 1-78 and 2-77 inhibited AR target gene expression and cell growth in prostate cancer cells in a BRD7-dependent manner at sub-micromolar concentrations." (PMID 38390898, 2024). "Increased cellular cholesterol and cholesterol-ester conversion are beneficial in AR-independent prostate-cancer growth." (PMID 39455589, 2024). "We explored the interplay between p300 and AR or ERG, which are the two most critical oncogenic transcription factors in prostate cancer cells, in AR-positive/ERG-positive VCaP cells." (PMID 38586029, 2024). "These enzymes are increasingly recognized as coregulators of AR16–19, and their inhibition significantly hinders the growth of AR-positive prostate cancer cells, including CRPC17,20,21." (PMID 38586029, 2024). "Pharmacological Stat5 inhibition provides a strategy to suppress androgen receptor gene transcription and prostate cancer growth." (PMID 38416822, 2024). "Prostate cancer (PCa) initially shows satisfactory response to therapies targeting the androgen receptor (AR)." (PMID 38214432, 2024). "Our study investigated how the inhibition of MED12 and CDK8/19 subunits affects cancer signaling pathways and cell processes in prostate cancer, focusing on AR activity and cell responsiveness to enzalutamide." (PMID 39253786, 2024).
prostate carcinoma (continued). "As mentioned in Section 1.3, degrading the AR has recently gained interest in the search for treating castration-resistant prostate cancer." (PMID 38339414, 2024). "EGCG downregulates androgen receptor expression and function, reducing the proliferation of androgen-dependent prostate cancer cells." (PMID 39725830, 2024). "CBPD-409 also exhibited superior cytotoxicity, i.e. had the lowest IC50, when compared to other published p300/CBP degraders, bromodomain inhibitors, or HAT domain inhibitors in AR-positive prostate cancer cell lines." (PMID 38586029, 2024). "Androgen hormones and their receptor play a vital role in normal prostate development, but androgen receptor (AR) is also the main driver in the development of prostate cancer." (PMID 38228924, 2024). "NSD2 inactivation also engenders increased dependency on the NSD1 paralog, and a dual NSD1/2 PROTAC degrader is preferentially cytotoxic in AR-dependent prostate cancer models." (PMID 39251788, 2024). "Quercetin, another flavonoid of Sappan lignum, was able to inhibit AR protein expression in androgen-responsive prostate cancer cell lines, thereby suppressing the expression of prostate-specific, androgen-regulated tumor markers." (PMID 39318781, 2024). "Treatment of prostate cancer relies predominantly on the inhibition of androgen receptor (AR) signaling." (PMID 38015476, 2024). "The progression of prostate cancer (PCa) relies on the activation of the androgen receptor (AR) by androgens." (PMID 38339274, 2024). "In the case of prostate cancer, the ideal candidate is AR, which is overexpressed as castration resistance occurs." (PMID 38201308, 2024). "NSD2 expression is abnormally induced in prostate cancer, where its inactivation impairs AR transactivation potential by disrupting over 65% of its cistrome." (PMID 39251788, 2024). "The treatment of AR-positive prostate cancer cells with AU-15330 reduced DNA accessibility at oncogenic enhancer elements and disrupted enhancer–promoter loops and AR and FOXA1 occupancy, thereby suppressing oncogenic gene expression." (PMID 38390898, 2024). "This study revealed that ARNTL, a circadian regulator, was an acquired fragile site after AR inhibition, providing new clues for the treatment of prostate cancer resistance." (PMID 39011396, 2024). "Flutamide, a selective AR antagonist used primarily for prostate cancer, has been tested for the treatment of FPHL in women." (PMID 39256806, 2024). "Altogether, we identify NSD2 as a novel subunit of the AR neo-enhanceosome that wires prostate cancer gene expression programs, positioning NSD1/2 as viable paralog co-targets in advanced prostate cancer." (PMID 38464251, 2024). "The phosphorylation of CREB promotes GPX4 transcription, inhibiting ferroptosis and conferring prostate cancer cells with resistance to androgen receptor antagonists." (PMID 38726001, 2024). "Clarifying the roles of MED12 and CDK8/19 in modulating AR and AR-Vs is crucial for understanding their impact on prostate cancer." (PMID 39253786, 2024). "Dysregulated androgen receptor (AR) activity is central to various diseases, particularly prostate cancer (PCa), in which it drives tumour initiation and progression." (PMID 39529201, 2024). "This relevance is highlighted by the profound restriction of GR binding sites to open chromatin sites in AR-positive prostate cancer cells, suggesting that GR replaces AR activity and drives enzalutamide resistance from these open chromatin sites." (PMID 39027480, 2024). "Clinical studies have determined that taxanes improve OS compared to treatment with antiandrogens and inhibitors of the AR signaling pathway for prostate cancer patients who test positive for AR-V7." (PMID 38339092, 2024).
prostate carcinoma (continued). "Flu is a classical androgen receptor antagonist that can directly bind to androgen receptors in prostate cancer cells, inhibit the production of prostate specific antigen (PSA), induce apoptosis, and suppress tumor growth." (PMID 38637848, 2024). "Several AR-signaling-associated lncRNAs such as PCAL7, PRKAG2-AS1 and HOXC-AS1 can act as diagnostic biomarkers for prostate cancer." (PMID 39199690, 2024). "Meanwhile, it was also proposed that the inhibitory functional of CD8+T cell-intrinsic AR pathway was suppressed directly by IFNG in prostate cancer immunotherapy." (PMID 38491510, 2024). "An incorrect result for file GSM3223711 (“VCaP shCt AR peaks”) shows that the top four labels were prostate cancer lines, though the correct answer was ranked fourth." (PMID 38534537, 2024). "Further research showed that TRIM24 functions as a coactivator of the AR, playing a pivotal role in disease progression by acting as an oncogenic transcriptional activator in prostate cancer cells." (PMID 39160596, 2024). "Treatment intensification with androgen deprivation therapy (ADT) and androgen receptor pathway inhibitors (ARPi) have led to improved survival in advanced prostate cancer." (PMID 38947889, 2024). "While miR-21-3p mimics reduce AR expression in cardiac fibroblasts in a diabetic cardiac fibrosis model in male rats, miR-21 mimics upregulate AR protein expression in prostate cancer cells." (PMID 38987854, 2024). "Prostate cancer is one of the most prevalent malignancies and is primarily driven by aberrant androgen receptor (AR) signaling." (PMID 39027480, 2024). "We showed that MED12 and CDK8/19 inhibition downregulate the AR response and that they both affect prostate cancer cell response to enzalutamide." (PMID 39253786, 2024). "Following the interrogation of our patient-derived models, we explored the growth inhibitory effect of Thio-2 across multiple prostate cancer cell lines with varying levels of AR protein expression." (PMID 38412481, 2024). "As a later manifesting response, we studied gene regulation related to DNA-damage, DNA-repair, cell cycle and AR-signaling that is relevant in prostate cancer progression." (PMID 38956684, 2024). "Kinesin family member 15 (KIF15) facilitates the interaction between USP14 and AR/AR-V7, promoting enzalutamide resistance in prostate cancer cells." (PMID 38702734, 2024). "Androgen-deprivation therapy or AR-axis targeted therapy, aiming to suppress AR or androgen signaling, is still the major therapeutic option for advanced prostate cancer." (PMID 38531859, 2024). "Our research indicates that in prostate cancer, the heightened expression of AR achieves this goal by facilitating the expression of PEX10, a process that can be suppressed by enzalutamide." (PMID 39097593, 2024). "Some Mediator complex subunits, such as MED1 and MED19, are cofactors of AR and enhance its transcriptional activity in prostate cancer." (PMID 39253786, 2024). "The authors present UBX‐390 as an optimized AR degrader with remarkable anti‐tumor activity in treating castration‐resistant prostate cancer." (PMID 38958553, 2024). "The therapeutic landscape for prostate cancer continues to evolve with deeper insights into AR signaling and resistance mechanisms." (PMID 39335158, 2024). "Targeting both AHR and AR signaling is a promising strategy to address the ethnic disparities in prostate cancer outcomes." (PMID 39600743, 2024). "Research has indicated that AR antagonists sensitize AR+ prostate cancer to ferroptosis by downregulating MBOAT2." (PMID 39097593, 2024). "The Androgen Receptor (AR) pathway is crucial in driving the progression of prostate cancer (PCa) to an advanced state." (PMID 39671399, 2024).
prostate carcinoma (continued). "KEGG analysis of mRNAs in the lncRNA-miRNA-mRNA regulatory network showed that GXYLT2 was enriched in other types of O-glycan biosynthesis, and AR was enriched in prostate cancer and oocyte meiosis pathways." (PMID 38649401, 2024). "Endocrine therapy in prostate cancer (PCa): Androgen (AR) signaling pathway drives proliferation and invasion in prostate cancer." (PMID 38398147, 2024). "AU-15330 effectively inhibits tumor growth and synergizes with the AR antagonist enzalutamide in a prostate cancer xenograft model." (PMID 39697230, 2024). "Taken together, these data indicate that menin functions as a tumor promoter in AR-positive prostate cancer primarily through the activation of AR and Myc signaling." (PMID 39336822, 2024). "RUNX1 expression has been shown to be regulated by AR in human prostate cancer and triple negative breast cancer cells in vitro and ReMap ChIP-seq data reveals AR binding sites on mouse Runx1 and -2 promoter and intronic areas." (PMID 38630262, 2024). "Androgen receptor (AR) is a transcription factor critical for prostate cancer development and progression." (PMID 38410785, 2024). "miR-346 also directly regulates androgen receptor (AR) expression in prostate cancer cells, where inhibition of miR-346 significantly increases AR transcriptional activity, mRNA, and protein levels." (PMID 38536780, 2024). "AR activation is central to the pathogenesis of prostate cancer, driving tumor growth and progression." (PMID 39335158, 2024). "Abnormal AR signaling contributes to different human diseases, including androgen insensitivity syndrome and prostate cancer." (PMID 38474604, 2024). "The benefits and limitations of AR antagonists as therapeutic strategies for prostate cancer were overviewed in our earlier review article." (PMID 38339414, 2024). "In prostate cancer, AhR interacts with AR signaling in a context-dependent manner, exhibiting both enhancement and inhibition of AR activity." (PMID 39184676, 2024). "Endocrine resistance driven by sustained activation of androgen receptor (AR) signaling pathway in advanced prostate cancer (PCa) is fatal." (PMID 38898473, 2024). "Subsequently, we analyzed MED12 protein expression in a panel of prostate cancer cell lines (AR-positive: LNCaP, 22Rv1, VCaP, and DuCaP; AR-negative: DU145 and PC3) and in 1 benign prostatic hyperplasia cell line (BPH1)." (PMID 39253786, 2024). "In this review, we will first outline the current prostate cancer treatment landscape, followed by an in-depth review of relatively newer prostate cancer therapeutics, focusing on AR-targeting agents under clinical development." (PMID 38201308, 2024). "Kaplan–Meier survival analysis based on TCGA survival data revealed that patients with prostate cancer who expressed more AR had shorter DFS." (PMID 38384328, 2024). "This revealed several lncRNAs upregulated with AR amplifications with many of them enriched in prostate cancer cells." (PMID 38396008, 2024). "Prostate cancer is driven by the androgen receptor (AR), an androgen-dependent transcription factor that promotes cell growth and proliferation." (PMID 39253786, 2024). "lncRNAs not only act as oncogenes to promote prostate cancer progression but also suppress the malignant phenotype of this tumor by inhibiting the AR signaling pathway." (PMID 39655078, 2024). "Silencing menin in AR-positive prostate cancer cell lines also reduces the expression of TMPRSS2, an androgen-responsive transmembrane serine protease that promotes prostate cancer growth and metastasis." (PMID 39336822, 2024). "This research emphasized AhR's role as a coactivator of AR, highlighting its potential in promoting prostate cancer progression." (PMID 39184676, 2024). "Prostate cancer is uniquely driven by androgen receptor signalling, and this knowledge has also influenced the paths of cancer metabolism research." (PMID 38969865, 2024).